CCNB1 (cyclin B1)
Diseases named in the same sentence as CCNB1 in open-access papers (continued):
Sharing a sentence is not in itself a finding about the gene and the disease.
lymphoma (9 papers, 2008 to 2025). A malignant (clonal) proliferation of B- lymphocytes or T- lymphocytes which involves the lymph nodes, bone marrow and/or extranodal sites. "Conversely, studies in lymphoma, thymoma and CRC have reported favorable outcomes associated with elevated CCNB1 expression, highlighting its tumor-type-specific prognostic role." (PMID 41614789, 2025). "Along with these results, QS1189 treatment induced G2/M arrest by decreasing the levels of cyclin B1, Aurora, and Cdc2 and then apoptosis in all lymphoma cells." (PMID 31076643, 2019). "We thus established that in both the assessed lymphoma cell lines, the expression levels of CDK1, CDK4, and Cyclin B1 were reduced following treatment with artesunate." (PMID 37719860, 2023). "Similarly, the suppression of BUB3, CCNB1, CDCA8, and CDK1 supported mitotic disruption and proliferative collapse in the HKB-11 lymphoma cells upon treatment with the N and UB combination." (PMID 40725093, 2025). "Moreover, 47 cell proliferation-associated genes were found downregulated in Ri-1 cells under hypoxia, including cyclin CCNB1, and cyclin-dependent kinases CDK14, CDK15, and CDK16, which have significant involvement in the lymphoma pathogenesis." (PMID 34440794, 2021).
multiple myeloma (9 papers, 2010 to 2024). "Expression in myeloma cells is highly correlated to CDC20 and CCNB1/2 expression, and leads to increased myeloma proliferation." (PMID 29100463, 2017). "6-O-angeloylplenolin (6-OAP) is a sesquiterpene lactone agent that has been previously demonstrated to inhibit the growth of multiple myeloma (MM) cells through mitotic arrest with accumulated cyclin B1." (PMID 24137368, 2013). "In myeloma cells, however, cyclin B1 silencing abrogated 6-OAP-induced mitotic arrest." (PMID 26474281, 2015). "Apcin could enhance the effect of TAME, leading to an increase in the number of cells in mitosis, a longer mitotic duration, and greater stabilization of cyclin B1, securin, and cyclin A. Combination of apcin and proTAME could promote apoptosis in multiple myeloma cells." (PMID 31669221, 2019). "Treatment of human myeloma cell lines with proTAME, an APC/C inhibitor, resulted in an accumulation of APC/CCdc20 substrate cyclin B1 and an accumulation of cells in metaphase." (PMID 26716651, 2016). "Moreover, CCNB1, AURKB, EZH2 and PSMA5 were also upregulated in the SPs from eight primary myeloma samples." (PMID 23469177, 2013).
squamous cell carcinoma (9 papers, 2006 to 2025). A carcinoma arising from squamous epithelial cells. "Consistent with our results, a study examining tumor samples from 41 patients with stage II-IV squamous cell carcinoma of the tongue found CCNB1 overexpression in 37% of the cases." (PMID 39795587, 2024). "With regard to histology, the expression of CCNB1 in adenocarcinoma or squamous cell carcinoma subtypes was remarkably higher than in normal tissues (P < 0.01)." (PMID 33632229, 2021). "There must be more biological significance of cyclin B1 than just proliferation in squamous cell carcinoma." (PMID 23722120, 2013). "Labelling index values increased on progression from normal larynx through laryngeal dysplasia to squamous cell carcinoma for Mcm-2 (P=0.001), Ki67 (P=0.0002), cyclin D1 (P=0.015), cyclin A (P=0.0001) and cyclin B1 (P=0.0004)." (PMID 16832409, 2006). "Notably, squamous cell carcinoma had more CCNB1 expression than adenocarcinoma, the difference is significant (P < 0.01)." (PMID 33632229, 2021). "Other key genes, such as CDC20, CCNB1, CHK1, and UBE2C, are well-known regulators of mitotic progression and therapeutic resistance in squamous carcinomas." (PMID 41323280, 2025).
triple-negative breast carcinoma (9 papers, 2016 to 2025). An invasive breast carcinoma which is negative for expression of estrogen receptor (ER), progesterone receptor (PR), and human epidermal growth factor receptor 2 (HER2). "CCNB1 overexpression has been found to be associated with worse outcomes in triple-negative breast cancer." (PMID 36982402, 2023). "The performance of our nomogram model in predicting triple-negative breast cancer was satisfactory, with CCNB1 being the most significant gene." (PMID 38609711, 2024). "Knockdown of IGFBP-6 in a triple-negative breast cancer cell line, MDA-MB-231, also resulted in a decrease in Cyclin B1 accumulation, demonstrating that our observations are not cell line specific." (PMID 41419198, 2025).
colon adenocarcinoma (8 papers, 2014 to 2022). "The crude water extract of Centella asiatica showed S and G2/M arrest in human colon adenocarcinoma-derived Caco-2 cells, accompanied with the accumulation of cyclin B1 protein." (PMID 32580345, 2020). "The crude water extract of Centella asiatica showed S and G2/M arrest in human colon adenocarcinoma-derived Caco-2 cells, accompanied with accumulation of cyclin B1 protein in the cells." (PMID 25401123, 2014). "The differential expression of CCNB1 was reported in a gene chip profile, between the CD133+ and CD133- subpopulations in the SW480 colon adenocarcinoma cell line." (PMID 32121037, 2020).
rhabdomyosarcoma (8 papers, 2015 to 2023). A rare aggressive malignant mesenchymal neoplasm arising from skeletal muscle. "Both mRNA and protein levels of cdk1 and CCNB1 were elevated in all NB cell lines and the human rhabdomyosarcoma cell line, RH-41, when compared to a human fibroblast cell line (NHDF)." (PMID 26029996, 2015). "NB cell lines derived from high-stage, aggressive tumors as well as the rhabdomyosarcoma cell line RH-41 all presented with high cdk1/CCNB1 expression independent of the MYCN amplification status." (PMID 26029996, 2015). "However, bioinformatics analysis exhibited that CCNB1 was significant up‐regulated in Rhabdomyosarcoma patient, which was not consistent with the finding in Neuro‐2a cells overexpressing Pax3." (PMID 33336498, 2021).
Alzheimer disease (7 papers, 2008 to 2024). A progressive, neurodegenerative disease characterized by loss of function and death of nerve cells in several areas of the brain leading to loss of cognitive function such as memory and language. "SMAD7 also demonstrates the strongest association with Neurobehavioral Disorders (NM), Alzheimer Disease (AD), and Stroke, while CCNB1 ranks second." (PMID 39840278, 2024). "This causes the aberrant accumulation of several anaphase promoting complex/cyclosome-Cdh1 targets in the damaged areas of Alzheimer’s disease brains, including Rock2 and Cyclin B1." (PMID 36588673, 2022). "For instance, in vivo evidence has revealed S phase entry in ischemic neurons and aberrant expression of mitotic cyclin B1 in degenerating neurons in Alzheimer’s disease." (PMID 22836916, 2012). "Interestingly, cyclin B1 accumulates in degenerating brain areas in Alzheimer’s disease and stroke, which are situations known to be associated with an excitotoxic-type neuronal death." (PMID 22836916, 2012). "In Alzheimer’s disease and stroke pathogenesis, APC/CCdh1 but not Cdc20, is expressed in post-mitotic mammalian neurons and the inactivation of Cdh1 by phosphorylation results in the accumulation of cyclin B1." (PMID 33218190, 2020). "In Alzheimer’s disease and stroke pathogenesis, APC/CCdh1, but not APC/CCdc20, is expressed in post-mitotic mammalian neurons, and the inactivation of Cdh1 by phosphorylation results in the accumulation of cyclin B1." (PMID 33260674, 2020).
head and neck cancer (7 papers, 2006 to 2019). A primary or metastatic malignant neoplasm affecting the head and neck. "Over expression of cyclin B1 has been demonstrated common in various tumor types, including colorectal, prostate, breast, esophagus, lung and head and neck cancers as well as Hodgkin and MALT lymphomas." (PMID 25978027, 2015). "Radio-resistance, early recurrence and metastasis are related to high CCNB1 (17.4-fold) expression in head and neck cancer as well as acquired radio-resistance, possibly through the activation of NFκB and other anti-apoptotic mechanisms." (PMID 22905093, 2012). "Key words:Cyclin B1, oral squamous cell carcinoma, verrucous carcinoma, head and neck cancer." (PMID 23722120, 2013).
nasopharyngeal carcinoma (7 papers, 2012 to 2025). A carcinoma arising from the nasopharyngeal epithelium. "Recent research has indicated that ITCH mediates SIX1 ubiquitination and influences the development of nasopharyngeal carcinoma via the CDC27-cyclin B1 signaling pathway." (PMID 40170095, 2025). "Circ-CCNB1 inhibits migration and invasion of nasopharyngeal carcinoma by promoting binding between NF90 and TJP1 mRNA, stabilizing TJP1 mRNA, and enhancing tight junctions between tumor cells." (PMID 36358938, 2022). "By revealing the mechanism by which circ-CCNB1 regulates the migration and invasion of nasopharyngeal carcinoma, it may provide a potential marker and target for the diagnosis and treatment of patients with nasopharyngeal carcinoma." (PMID 36358938, 2022).
oral cancer (7 papers, 2013 to 2025). "Most of the studies have focused on G1-S transition, but there are very few published research papers on G2-M transition using cyclin B1 among these two variants of oral carcinoma." (PMID 23722120, 2013). "In oral cancer patients, we found that co-expressions of high PFKFB3/low p27 or high PFKFB3/high cyclin B1 or Slug were associated with poor DSS." (PMID 37919747, 2023). "Accordingly, CCNB1 phosphorylation was decreased in oral cancer cells." (PMID 31387297, 2019). "BI6727 reduced CCNB1 expression and phosphorylation in oral cancer cells." (PMID 31387297, 2019).
psoriasis (7 papers, 2022 to 2025). An autoimmune condition characterized by red, well-delineated plaques with silvery scales that are usually on the extensor surfaces and scalp. "In psoriasis, CCNB1 is closely associated with cell cycle regulation, highlighting its role in controlling keratinocytes proliferation." (PMID 40406126, 2025). "CCNB1 (Cyclin B1) has been considered to support the release of key molecular targets in psoriasis through the regulation of mast cell activation and macrophage polarization." (PMID 40560938, 2025). "In psoriasis, the five diagnostic hub genes (KIF4A, DLGAP5, NCAPG, CCNB1, and CEP55) were predominantly expressed in keratinocytes, with significantly higher expression levels in patient samples compared to controls." (PMID 40406126, 2025). "Importantly, among the DEGs, the proliferation-related genes, such as CDK1 and CCNB1, are likely important targets for treating psoriasis by oxymatrine." (PMID 35721124, 2022). "Therefore, abnormal expression of CCNB1 may accelerate the cell cycle, contributing to excessive proliferation of keratinocytes in psoriasis and impaired repair of intestinal epithelial cells in CD." (PMID 40406126, 2025). "CDK1 and CCNB1 may be important targets of oxymatrine in the treatment of psoriasis." (PMID 35721124, 2022). "Moreover, the changes in DEGs represented by CDK1 and CCNB1 expression may be important biomarkers for oxymatrine efficacy in the treatment of psoriasis." (PMID 35721124, 2022). "The expression of claudin, cyclin B1, cyclin D1, filaggrin, phospho-histone H2AX, kallikrein 7, Ki67, loricrin, NFAT5, and periplakin was assessed on punch biopsies obtained from eight psoriasis and six atopic eczema patients." (PMID 40559228, 2025). "This integrative approach highlighted KIF4A, DLGAP5, NCAPG, CCNB1, and CEP55 as key shared biomarkers for both psoriasis and CD." (PMID 40406126, 2025). "In the psoriasis dataset (GSE13355), the AUC values for KIF4A (AUC = 0.99), DLGAP5 (AUC = 1), NCAPG (AUC = 0.99), CCNB1 (AUC = 0.99), and CEP55 (AUC = 0.99) exhibited exceptional diagnostic performance, with all values exceeding 0.7." (PMID 40406126, 2025). "In the psoriasis validation cohort (GSE14905), the AUC values for KIF4A, DLGAP5, NCAPG, CCNB1, and CEP55 were 0.96, 0.97, 0.96, 0.98, and 0.93, respectively." (PMID 40406126, 2025). "Related research has found that the cell cycle is significantly shortened in patients with psoriasis and that high expression of CDK1 and CCNB1 promotes keratinocyte proliferation observed in psoriasis." (PMID 35721124, 2022). "Specifically, LINC02159 showed a positive correlation with CCNB1, whereas LINC01206 was positively correlated with both CCNB1 and CCNE1, suggesting that upregulated lncRNAs may coordinate with cell cycle genes to drive psoriasis progression." (PMID 40670887, 2025).
renal carcinoma (7 papers, 2016 to 2025). A carcinoma arising from the epithelium of the renal parenchyma or the renal pelvis. "We further tested this using a panel of six renal cancer cell lines, in which three have loss of function mutations in PBRM1, and we found that PBRM1 deficient cells are considerably more sensitive to CCNB1 depletion than the PBRM1 proficient cell lines, suggesting potential clinical implications." (PMID 40011561, 2025). "Furthermore, the let-7 family targets cell cycle control proteins such as CDK1, CDK 2, CDK6 and cyclin B1 in various tumours including renal cancer cells." (PMID 36076967, 2022).
thyroid cancer (7 papers, 2002 to 2022). "Similar results of the CUDC-907-mediated blockage of the S and G2/M phases were shown for pancreatic and thyroid cancers via the downregulation of the cell cycle regulators cyclin B1, AURKA, and PLK1." (PMID 35205815, 2022). "Our data showed that SFN-treated thyroid cancer cells were arrested in G2/M phase, which was accompanied by a decline in the levels of Cdk1, Cdk2, Cyclin B1 and Cdc25C and an increase in the levels of Chk1 and p21." (PMID 26312762, 2015). "Furthermore, our recent study showed that cyclin A expression level increased with dedifferentiation of thyroid carcinoma and cyclin B1 overexpression was found exclusively in undifferentiated carcinoma (manuscript submitted)." (PMID 12085185, 2002). "LIFR-AS1 was also found to be significantly upregulated in thyroid cancer tissues and cell lines, and its silencing reduced the viability and inhibited the proliferation of human thyroid cancer cells by inducing G2/M cell cycle arrest, possibly through the suppression of cyclin B1 and CDK1." (PMID 35071590, 2022). "However, the expression levels of CCNB1 and RACGAP1 genes were significantly downregulated in at least one histological subtype of thyroid carcinoma." (PMID 30774662, 2019).
retinoblastoma (6 papers, 2017 to 2024). A malignant tumor that originates in the nuclear layer of the retina. "CCNB1 (Cyclin B1) has been linked to several diseases, including Retinoblastoma and Laryngeal Squamous Cell Carcinoma." (PMID 39118438, 2024). "Apart from cellular stress response proteins, cell cycle proteins such as CDK1, CDK11, MCM2, MCM3, MCM5, and CCNB1 were also found to be hyperphosphorylated in retinoblastoma, implicating accelerated cell cycle progression." (PMID 29914080, 2018). "The cells enriched in state-5 at the terminal of the branch shared a highly similar global expression profile with retinoblastoma cells that possess cell cycle (UBE2C, PTTG1, CCNB1) and proliferation (MKI67) properties." (PMID 34815392, 2021). "Notwithstanding we can investigate other markers which distinguish retinomas from Rb tumors, for example Ki67 or Cyclin B1, both of which are highly expressed in Rb, but not retinoma samples." (PMID 34003213, 2021).
viral infection (6 papers, 2010 to 2023). "Conversely, we observed a linear increase of cyclin B1 during virus infection for all three recombinant VVs; thus recombinant VVs possibly induced cell cycle arrest in mitosis." (PMID 28951871, 2017). "Therefore, we examined the accumulation of geminin and two other APC substrates, cdc6 and cyclin B1, in mutant virus infection." (PMID 20333247, 2010). "It has been previously determined that during viral infection, the subcellular distribution of CDK1-cyclin B1 is altered, which is essential for the active CDK1-cyclin B1 to regulate virus replication." (PMID 36602364, 2023).
meningioma (5 papers, 2017 to 2023). A generally slow growing tumor attached to the dura mater. "2D meningioma cells were subdivided into five clusters including proliferating cells expressing the FOXM1 target genes CCNB1 and TOP2A, cells enriched for metabolic pathways, and cells enriched for extracellular matrix organization and integrin interaction pathways." (PMID 32968068, 2020). "Meningioma cells with knockdown of OGN also demonstrated significantly reduced cell proliferation and expression of the cell cycle markers cyclin A2 and cyclin B1, compared to cells with stable expression of OGN." (PMID 28923059, 2017).
oral squamous cell carcinoma (5 papers, 2013 to 2022). "The activation of the CDK1-cyclin B1 complex leads to mitotic entry, and overexpression of cyclin B1 and CDK1 proteins is associated with progression of human oral squamous cell carcinoma." (PMID 26110572, 2015). "However overlap of nuclear overexpression among grades precludes use of cyclin B1 over expression as an indicator for grading and also cyclin B1 is not a good indicator to assess the variants of oral squamous cell carcinoma." (PMID 23722120, 2013).
sarcoma (5 papers, 2019 to 2025). A usually aggressive malignant neoplasm of the soft tissue or bone. "We found that increased expression of CDK1 and CCNB1 in RMS is related with negative prognosis in sarcoma sufferers." (PMID 31870357, 2019). "By analyzing data from TCGA sarcoma cohort, we further confirmeda strong positive correlation between RRM2 and cyclin B1, cyclin E1,and CHEK1 expression, as well as a negative correlation with TP53expression." (PMID 40834268, 2025).
stomach cancer (5 papers, 2018 to 2021). "Our data consistently provided evidence that CREPT is highly expressed in gastric tumors where Cyclin B1 is overexpressed." (PMID 30518842, 2018). "Our study provides a mechanism by which gastric tumor cells maintain their high proliferation rate via coordination of Aurora B and CREPT/RPRD1B on the expression of Cyclin B1." (PMID 30518842, 2018).
brain cancer (4 papers, 2019 to 2024). A primary or metastatic malignant neoplasm affecting the brain. "Previous studies have suggested that in brain cancer cells, cell-cycle arrest was achieved by downregulating the expression of cdc2 and cyclin B1 proteins and disrupting the cdc2/cyclin B1 complex through the upregulation of GADD45β." (PMID 37886957, 2023).
chondrosarcoma (4 papers, 2014 to 2021). A malignant cartilaginous matrix-producing mesenchymal neoplasm arising from the bone and soft tissue. "In addition, we found that the expression of p-Rb and cyclin B1, which have been demonstrated to be associated with G2/M stage arrest, were decreased in chondrosarcoma cell lines when treated with siBMPR2 for 48 h." (PMID 25501832, 2014). "One study showed that the diacerein resulted in the viability reduction of chondrosarcoma cells and G2/M cell cycle arrest by cyclin B1/ Cdc2 downregulation." (PMID 27903976, 2017). "Our results demonstrate for the first time that the SYSADOA diacerein decreased the viability of human chondrosarcoma cells and induces G2/M cell cycle arrest by CDK1/cyclin B1 down-regulation." (PMID 26555773, 2015). "Our results demonstrate for the first time that diacerein decreased the viability of human chondrosarcoma cells and induces G2/M cell cycle arrest by CDK1/cyclin B1 down-regulation." (PMID 26555773, 2015).